IL1B (interleukin 1 beta)
Diseases named in the same sentence as IL1B in open-access papers (continued):
Sharing a sentence is not in itself a finding about the gene and the disease.
leptospirosis (18 papers, 2012 to 2025). A contagious bacterial infection caused by spirochetes of the genus Leptospira. "The immunoprotective role of IL-10 during leptospirosis is to mitigate the deleterious effects caused by the increase in pro-inflammatory cytokines, such as interleukin 1 β (IL-1β), which is related to organ failure in infected hosts." (PMID 34070451, 2021). "Taken together, these observations support the indication that IL1β polymorphisms are involved in susceptibility to bacterial infections, such as leptospirosis." (PMID 25255143, 2014). "Cytokines, particularly TNF-α, IL-6, IL-1β and IL-10, have been found to be higher in severe and even fatal forms of human leptospirosis compared to milder infections." (PMID 40986630, 2025). "In comparison, a 2015 study measured IL-1β levels in the sera of 47 patients with acute leptospirosis at a mean of 40 pg/mL." (PMID 40986630, 2025). "Similar IL-1β levels were found in a 2013 Brazilian study, though leptospirosis patients exhibited higher levels of IL-1β than controls." (PMID 40986630, 2025). "A previous systematic review showed elevated levels of cytokines (IL-1β, IL-2, IL-4, IL-6, IL-8, IL-10, TNFα) in severe human leptospirosis compared with mild leptospirosis." (PMID 39729468, 2024). "TLR2 involvement during the pathogenesis response against leptospirosis was observed through the decrease of IL1β, TNFα, IL6, NFκB, and IL10 secretion/expression due to deficient/knocked down of the TLR2 receptors." (PMID 39729468, 2024). "Then, a cascade of inflammation is activated in the renal tubular cells, as leptospirosis induces interleukin (IL)-1β and IL-18 secretion from human macrophage cells through reactive oxygen species and cathepsin B mediated-NLRP3 inflammasome activation." (PMID 35203344, 2022). "Consistent with IL-1β found in blood of leptospirosis patients, another study showed that IL-1β and IL-18 were also produced in human cells through NLRP3 activation." (PMID 35937697, 2022). "Especially, TNF-α and the interleukins IL-1β, IL-2, IL-4, IL-6, IL-8, and IL-10 were elevated in severe leptospirosis cases, whereas TNF-α, IL-6, IL-8, IL-10, interferon-γ, and soluble TNF receptor 1 were elevated in high fatality cases." (PMID 35237527, 2021). "Although, the review produced valuable data on the possible role of cytokines in leptospirosis disease severity, there were equivocal findings with regards to IL-1β, TNF-α and IL-10/TNF- α ratio among the selected studies." (PMID 32264832, 2020). "It has also been suggested that, among other factors, polymorphisms in IL-4 and IL-4R and IL-1β, IL-12R, and CISH (multiple cytokines inducible SH2-containing protein gene) correlated with susceptibility to leptospirosis." (PMID 28270811, 2017). "Leptospirosis-susceptible hamsters showed strong expression of IL-1β, IL-6, TNF-α, and COX-2 in infected organs, whereas leptospirosis-resistant mice showed accelerated expression of the anti-inflammatory IL-10." (PMID 26824356, 2016). "This study deciphered haemorrhage as the earliest manifestation of severe leptospirosis and high levels of IL-1β, CXCL10/IP-10, CCL3/MIP-α, neutrophils and low levels of lymphocytes and platelets serve as a cumulative panel of biomarkers in severe leptospirosis." (PMID 35584087, 2022). "However, the present review found IL-1β to be low among leptospirosis patients, IL-6 to be elevated and TNF-α to be equivocal." (PMID 32264832, 2020). "As the efficacy of Dox against leptospirosis is acceptable, the inhibition of IL-1β levels may be a new treatment strategy against leptospirosis." (PMID 28791016, 2017). "The cytokine profile revealed that the levels of at least sixteen cytokines were significantly elevated in the leptospirosis patients’ sera, including the major proinflammatory factors IL-1β, IL-6 and TNF-α, and the major anti-inflammatory factors IL-4, IL-10 and IL-13." (PMID 22870312, 2012).
leptospirosis (continued). "Results showed that genotypes -511GG (OR = 1.6, 95% CI 1.01–2.56, p = 0.04) in IL1β, +1196CG (OR = 2.0, 95% CI 1.26–3.27, p = 0.003) in IL12RB1, -292TA (OR = 1.8, 95% CI 1.06–2.1, p = 0.03) and +3415CG (OR = 1.8, 95% CI 1.08–3.08, p = 0.02), both in CISH, have increased risk to leptospirosis." (PMID 25255143, 2014). "Significantly higher concentrations of IL-1β, IL-2, IL-4, IL-6, IL-8, IL-10, IL-17A, and TNF-α were found in sera of leptospirosis patients." (PMID 35927283, 2022). "Several earlier studies have identified significant expression of IL-1β, IL-2, IL-4, IL-6, IL-8, IL-10 and TNF-α in severe leptospirosis." (PMID 35584087, 2022). "Pro-inflammatory cytokines and enzymes which were IL-1β, IL-6, TNF-ɑ, IFN-γ and COX-2 and chemokines CXCL10/IP-10 and CCL3/MIP-α showed upregulation as reported in both human and animal leptospirosis." (PMID 35584087, 2022). "IL-1b, IL-2, IL-4, IL-6, IL-8, IL-10 and TNF-α levels were found to be significantly higher in severe than in mild leptospirosis." (PMID 32264832, 2020). "IL-1β, IL-6 and TNF-α were proposed to be pro-inflammatory cytokines which enhance the inflammatory response in leptospirosis." (PMID 32264832, 2020). "The lack of IL-1β secretion in patients with leptospirosis is an important finding because IL-1ß is a central orchestrator of inflammation, and is a marker for many bacterial infections that cause sepsis." (PMID 40986630, 2025). "High levels of IL-1β, CXCL10/IP-10, CCL3/MIP-α, neutrophils and low levels of lymphocytes and platelets might serve as a cumulative panel of biomarkers in severe leptospirosis." (PMID 35584087, 2022). "In addition, studies also reported IL-1β, IL-12P70 and TNF-α, levels as low or undetectable in leptospirosis patients and healthy controls." (PMID 32264832, 2020). "Nevertheless, the mechanism by which IL1β and IL12RB1 mediates protection against human leptospirosis is unknown." (PMID 25255143, 2014). "The increased expression of IL-1β, CXCL10/IP-10, CCL3/MIP-α, high neutrophils and low lymphocytes and platelets production observed in the present study indicate that these parameters could serve as a cumulative panel of biomarkers in severe leptospirosis." (PMID 35584087, 2022). "The early expression of IL-1β, CXCL10/IP-10 and CCL3/MIP-α, increase of neutrophils and decrease of lymphocytes and platelets suggesting that these parameters could be used as a cumulative panel for potential biomarkers in severe leptospirosis." (PMID 35584087, 2022). "Notably, we observed the secretion/mRNA expression of several cytokines (IL6, IL8, IL-1β, TNFα, IFNγ, IL10, CCL2/MCP-1, CCL10, COX2, CXCL1/KC, CXCL2/MIP2) and immune effectors (hBD2, iNOS, Fibronectin, Oxygen, and Nitrogen reactive species) as key aspects of host TLR2 responses during leptospirosis." (PMID 39729468, 2024). "Taken all these data together, we suggest that high levels of IL-1β, CXCL10/IP-10, CCL3/MIP-α, neutrophils and low levels of lymphocytes and platelets could serve as a cumulative panel of potential biomarkers in the disease progression from mild to severe in leptospirosis." (PMID 35584087, 2022). "For this, we evaluated the mRNA expression of a panel of immune related cytokines (IL-1α, IL-1β, IL-8, IL-10, TNF-α, TGF-β) and enzymes (5-LO, iNOS) in blood leukocytes from dogs with AKI and leptospirosis, including dogs with and without LAPH." (PMID 26824356, 2016).
unstable angina (18 papers, 2013 to 2022). "Several studies have shown a positive association between the serum concentration of TMAO and inflammation biomarkers, such as usCRP, IL-1β, and so on, in general population or patients with stable angina." (PMID 36384389, 2022). "Increased circulatory levels of IL-1β in patients with unstable angina indicates its contribution to the acute disease process." (PMID 24736319, 2014). "Studies showed that IL-1B was at higher levels in UA patients, comparing both stable angina ones and control subjects in peripheral blood." (PMID 23762142, 2013). "In patients with unstable angina, oxLDLs may contribute to monocyte overproduction of some cytokines and above all to that of IL-6 and IL-1β, by upregulating TLR4 expression." (PMID 25757594, 2015). "Among the particularly excellent compounds for unstable angina, liquiritin (MOL004903) reduces mRNA expression of TNFα, IL-6, and IL-1β, inhibits inflammatory cell migration, suppresses oxidative stress and apoptosis in the heart, and improves metabolism." (PMID 35140797, 2022). "By the integration of the DEGs of healthy/MI and unstable angina/MI, the potential targets of Yixinyin for the treatment of MI (ALDH2, C5AR1, CFOS, IL1B, TLR2, TRXR1) have been obtained." (PMID 34799616, 2021).
vascular dementia (18 papers, 2012 to 2026). A degenerative vascular disorder affecting the brain. "Interaction between vascular dementia status and systemic infection was seen for IL-13 and IL-1β (as shown by one-way ANOVA) and in addition, GM-CSF and IL-8." (PMID 33723589, 2021). "Several papers demonstrate that EA-induced anti-inflammatory actions improve cognition and suppress neuroinflammatory factors such as TNF-α and IL-1β involved in toll-like receptor (TLR) signaling in animal models of vascular dementia." (PMID 31836020, 2019). "As was reported, the mRNA expression of TNF-α, IL-6 and IL-1β was decreased in rats of the electroacupuncture group compared with the vascular dementia (VD) group." (PMID 31049031, 2019). "Levels of IL-1β have been shown to be higher in the cerebrospinal fluid (CSF) of AD patients than in patients with vascular dementia or control patients." (PMID 25540075, 2014). "Moreover, it exacerbates vascular dementia by producing IL-18, IL-1β, and the N-terminal fragment of GSDMD, which also contributes to neuronal cell death." (PMID 40326096, 2025). "The significantly increased serum levels of IL-4 and IL-5 in the MCI/AD group correspond with findings in a previous study that reported elevated IL-4, IL-5, IL-1β, TNF-α, IFN-γ, G-CSF, and MIF-1b levels in patients with vascular dementia." (PMID 37760836, 2023). "In another study, it was shown that the NF-κB, TNF-α, and IL-1β levels in the hippocampus were significantly increased in rats with vascular dementia that were not treated with nimodipine." (PMID 41464815, 2025). "In contrast, IL-13 and IL-1β levels were lower in vascular dementia patients with than without infection." (PMID 33723589, 2021). "The 0.2 g/kg Cs-C-Q80 treatment only slightly downregulated the TNF-α and IL-1β, while 1.0 g/kg Cs-C-Q80 treatment significantly inhibited the TNF-α and IL-1β increasing (P<0.05), suggesting the involvement of the inflammation-resistant of Cs-C-Q80 treatment on vascular dementia." (PMID 30662512, 2018). "However, as phlorizin improved the increased IL‐1β gene expression in ACAS mice it may not affect hippocampal neuronal death, leading to VCI, through an inhibitory action against neuronal SGLT1 in a mouse model of ACAS‐induced vascular dementia." (PMID 34586752, 2021).
acute myeloid leukemia (17 papers, 2010 to 2025). Acute myeloid leukemia (AML) is a group of neoplasms arising from precursor cells committed to the myeloid cell-line differentiation. "These specific effects of SOCS2 in the context of IL-1β are important because IL-1β-signaling is known to be associated with tumor progression in certain myeloid disorders such as acute myeloid leukemia (AML) and chronic myeloid leukemia (CML)." (PMID 31775389, 2019). "GATA2 was found to be mediated by p38/ERK-dependent phosphorylation in acute myeloid leukemia cells and to be involved in the transcriptional regulation of several pro-inflammatory cytokines, including IL-1β." (PMID 37208193, 2023). "Accordingly, IL-1β has been identified as a key cytokine in inflammation-related myeloid malignancies, including acute myeloid leukemia (AML) and chronic (CML) myeloid leukemia, as it supports cellular expansion and hence disease progression." (PMID 31775389, 2019). "Similarly, in the setting of acute myeloid leukaemia, which is characterised by clonal expansion of myeloid progenitors, IL‐1β was found to be required for pathogenesis." (PMID 33204425, 2020). "In acute myeloid leukemia (AML), C/EBPα DM alleviates CD8+ T cell immunosuppression by inhibiting autophagy-associated IL-1β secretion." (PMID 41246345, 2025). "RSV is able to suppress the production of IL1β and NF-kB in a dose-dependent manner in the acute myeloid leukemia (AML) cell lines OCI/AML3 and OCIM2." (PMID 28555002, 2017). "It has been shown that some cancer types such as invasive breast cancer, melanoma, prostate cancer, acute myeloid leukemia (AML), chronic myeloid leukemia (CML), and gastric tumors overexpress IL-1β." (PMID 33026575, 2021).
adenoma (17 papers, 2008 to 2025). A neoplasm arising from the epithelium. "Although IL-1β levels gradually increase with the transformation of healthy colon tissue to adenoma and further to CRC56, tumor-associated ILCs displayed CD86 expression only in three out of thirteen CRC cases analyzed." (PMID 32341343, 2020). "Decreased IL-2 concentration during the trial increased the risk of any adenoma recurrence (4th vs 1st quartile, OR=1.68, 95% CI=1.13–2.49), whereas decreased IL-1β or IL-10 reduced the risk of advanced adenoma recurrence (OR=0.37, 95% CI=0.15–0.94; OR=0.39, 95% CI=0.15–0.98, respectively)." (PMID 20924374, 2010). "Our data found that IL-1β expression gradually increases from a slight rise in adenoma to a more substantial over-expression in carcinoma tissues." (PMID 40149674, 2025). "In the Same group, the levels of MIP-1b in the adenoma group were significantly higher than those in the hyperplasia group, while IL-12p70, IL-17E, IL-1b and MIP-1a were all lower than those in the hyperplasia group." (PMID 37029172, 2023). "The expression of IL-4, TNF-α, COX-2, and IL-1β is higher in serrated adenomas than in adenomas, but the expression of IL-10 shows the opposite trend." (PMID 35884974, 2022). "Histopathologic analysis of lungs from anti–IL-1β–treated mice revealed that the percentages of lung area occupied by tumor and adenoma and adenocarcinoma lesions were reduced by 47.5% and 53%, respectively." (PMID 35471938, 2022). "In addition, B. vulgatus showed positive correlation with inflammatory markers (i.e. myeloperoxidase and IL-1β levels), tumor numbers, and high-grade adenoma, especially, developed mucosal and submucosal invasive adenocarcinoma at the distal part of the colon." (PMID 34249773, 2021). "Furthermore, the abundance of B. vulgatus was positively correlated with inflammatory markers (DAI score, and levels of MPO and IL-1β), developed tumor numbers, and high-grade adenoma developed mucosal and submucosal invasive adenocarcinoma, especially, at the distal part of the colon." (PMID 34249773, 2021). "Analysis of TNF-α, CXCL1, IL-1β, IL-10 protein and TGF-β mRNA levels in colonic tissue segments devoid of obvious adenomas revealed the expected increases in these cytokines in the AOM/DSS mice were not affected by M(IL4) treatment." (PMID 34691050, 2021). "Furthermore, wogonoside dramatically decreased the secretion and expression of IL-1β, IL-6 and TNF-α as well as the nuclear expression of NF-κB in adenomas and surrounding tissues." (PMID 27102438, 2016). "Analyses of the proinflammatory cytokines TNF-α, IL-6, and IL-1β in the serum of participants with colorectal adenomas compared to non-adenoma controls revealed that the presence of adenomas do not lead to systemic elevation in the levels of these cytokines." (PMID 25884547, 2015). "The nitroproteomic data of human pituitary adenomas show that TNF and IL1B are the key nodes in their pathway networks; and that p38-MAPK signaling is the significant canonical pathway that participates in an oxidative-stress response in an adenoma." (PMID 20426862, 2010). "research, which found elevated circulating IL1B levels in cancer patients but not in those with adenomas, aligning with our observations that IL1B may differentiate cancer from adenomatous conditions." (PMID 38979413, 2024).
Atrophy (17 papers, 2011 to 2026). Any weakening or degeneration, especially through lack of use. "Differentially from what we found, *2 allele carriers exhibited higher IL-1β expression with severe degrees of inflammation and a close association with atrophy in the antrum and corpus in Japanese and German populations." (PMID 36838318, 2023). "Additionally, IL-1β is the strongest inhibitor of gastric acid found thus far, and the continuous secretion of low levels of gastric acid into the stomach will promote the occurrence and development of atrophy and lead to an increase in the risk of development of GC." (PMID 37687125, 2023). "Ablation of NG2 glial cells produced defects in hippocampal neurons due to excessive neuroinflammation via activation of the interleukin-1 beta (IL-1β) pro-inflammatory pathway, resulting in hippocampal atrophy." (PMID 28195192, 2017). "We aimed to investigate if IL-1β activation via the Nlrp3 inflammasome is involved in inflammation-induced atrophy." (PMID 28097512, 2017). "It is well established that the serum levels of proinflammatory cytokines, particularly IL-1β and TNF-α, are elevated in cachectic patients contributing to muscle atrophy." (PMID 26064425, 2015). "Likewise, it is essential to highlight the correlation between elevated mediator levels and increased marginal bone atrophy in cigarette smokers (MMP-9 and IL-1β) and e-cigarette users (IL-1β)." (PMID 37526741, 2023).
colorectal tumor (17 papers, 2015 to 2025). "Activation of NLRP3 and release of IL-1β was also reported to cause overproduction of 5-hydroxytryptamine in colorectal tumors, which accelerates CAC development." (PMID 38898209, 2024). "Indeed, several bacterial species have been associated to CRC, and Streptococcus gallolyticus can infect colorectal tumors and has been linked to local IL1β and PTGS2 expression." (PMID 32168749, 2020). "In this grouping, IL1B as another inflammatory system gene that is famous in gastrointestinal system and promotes invasion in colorectal tumor as well." (PMID 30774816, 2018). "Altogether, our results suggest that targeting basal IL-1β crosstalk between CAFs and colorectal tumor cells may inhibit the pro-tumorigenic function of CAFs." (PMID 37460545, 2023). "Therefore, in addition to elucidating a critical role for caspase-11 in IL-1β production in established colorectal tumours, our data show that, once initiated, IL-1β signalling drives caspase-11 upregulation in BMDM, IECs and CT26 murine CRC cells, to further promote its pro-inflammatory effects." (PMID 30538296, 2019). "In the AOM/DSS-induced orthotopic CRC model, KGM-PTX/CSM significantly inhibited colorectal tumor growth, improved survival rates, and suppressed inflammatory cytokine expression (TNF-α, IL-1β, IL-6, and IL-10) in serum and colorectal tissues." (PMID 40528838, 2025). "In present study, inhibition of Notch signaling by the γ-secretase inhibitor DAPT significantly reduced NOTCH1, JAGGED1, LEPTIN, ObRb, IL-1β, VEGF-A, and VEGFR1 mRNA levels in colorectal tumor tissues compared to control groups." (PMID 38152619, 2023). "The blockade of Notch signaling by the γ-secretase inhibitor DAPT significantly reduced NOTCH1, JAGGED1, LEPTIN, ObRb, IL-1β, VEGF-A, and VEGFR1 mRNA levels in colorectal tumor tissues." (PMID 38152619, 2023). "Aggravation of colorectal tumors; induction of inflammatory cytokines and pathways (TNF-α, IL-1β, IL-6, IL-10)." (PMID 35893902, 2022). "IL1β-stimulated-NCF-CM induces migration and differential sensitivity to oxaliplatin in colorectal tumor cells." (PMID 34066976, 2021). "Besides its role in acute inflammation, IL-1β is also a key mediator of chronic inflammation-induced pathological changes in IBD and can promote colorectal tumour development." (PMID 35326545, 2022).